COX5A (cytochrome c oxidase subunit 5A)
Description:
Component of the cytochrome c oxidase, the last enzyme in the mitochondrial electron transport chain which drives oxidative phosphorylation. The respiratory chain contains 3 multisubunit complexes succinate dehydrogenase (complex II, CII), ubiquinol-cytochrome c oxidoreductase (cytochrome b-c1 complex, complex III, CIII) and cytochrome c oxidase (complex IV, CIV), that cooperate to transfer electrons derived from NADH and succinate to molecular oxygen, creating an electrochemical gradient over the inner membrane that drives transmembrane transport and the ATP synthase. Cytochrome c oxidase is the component of the respiratory chain that catalyzes the reduction of oxygen to water. Electrons originating from reduced cytochrome c in the intermembrane space (IMS) are transferred via the dinuclear copper A center (CU(A)) of subunit 2 and heme A of subunit 1 to the active site in subunit 1, a binuclear center (BNC) formed by heme A3 and copper B (CU(B)). The BNC reduces molecular oxygen to 2 water molecules using 4 electrons from cytochrome c in the IMS and 4 protons from the mitochondrial matrix.
Synonyms: COX-VA; COX; MC4DN20; VA
Tractability: Small molecule: a structure with a bound ligand is known. Antibody: UniProt places it where antibodies can reach, with high confidence. PROTAC: UniProt records ubiquitination sites on it; ubiquitination databases record sites on it; its protein half-life has been measured.
Gene: Protein-coding gene on chromosome 15 (74,919,791 to 74,939,351, reverse strand). Ensembl gene ENSG00000178741.
Subcellular location: Mitochondrion inner membrane
Pathways (Reactome):
Metabolism: Complex IV assembly; Respiratory electron transport
Cellular responses to stimuli: Cytoprotection by HMOX1
Metabolism of proteins: Mitochondrial protein degradation
Gene Ontology:
Molecular function: protein binding; cytochrome-c oxidase activity; electron transfer activity
Biological process: cellular respiration; mitochondrial electron transport, cytochrome c to oxygen; oxidative phosphorylation; proton transmembrane transport
Cellular component: mitochondrial inner membrane; mitochondrial membrane; mitochondrion; respiratory chain complex IV; mitochondrial intermembrane space
Genetic constraint (gnomAD): Loss-of-function variants: 2 observed, 7.67 expected, observed/expected ratio (o/e) 0.26, 90% interval 0.11 to 0.82. That is too few expected variants to judge how well the gene tolerates losing a copy. Missense variants: 116 observed, 124.24 expected, observed/expected ratio (o/e) 0.93, 90% interval 0.8 to 1.09. Synonymous variants: 54 observed, 49.61 expected, observed/expected ratio (o/e) 1.09, 90% interval 0.87 to 1.37.
Gene-disease validity (ClinGen):
ClinGen rates the evidence that COX5A causes each of these diseases.
mitochondrial disease (autosomal recessive): Moderate.
Homologues: Orthologues: macaque COX5A (96% identical), pig COX5A (90% identical), guinea pig COX5A (87% identical), mouse Cox5a (85% identical), rat LOC100361008 (85% identical), rat LOC100361008 (83% identical), rabbit COX5A (77% identical), tropical clawed frog cox5a (76% identical), zebrafish cox5aa (70% identical), zebrafish cox5ab (65% identical), Drosophila melanogaster COX5A (45% identical), Caenorhabditis elegans cox-5A (39% identical).
Diseases named in the same sentence as COX5A in open-access papers:
COX5A is named in the same sentence as 55 diseases in open-access papers, as found by Europe PMC text mining. Sharing a sentence is not in itself a finding about the gene and the disease. The quoted sentences say what the papers report.
Alzheimer disease (6 papers, 2020 to 2025). A progressive, neurodegenerative disease characterized by loss of function and death of nerve cells in several areas of the brain leading to loss of cognitive function such as memory and language. "Previous studies have found that abnormalities in COX5A are associated with growth retardation, abnormal lactate metabolism and aging-related diseases such as Parkinson’s disease and Alzheimer’s disease." (PMID 37007963, 2023). "However, little is known on the role of COX5A in the development and progress of Alzheimer’s disease." (PMID 32754029, 2020). "The Parkinson’s disease and Alzheimer’s disease pathways in the SncaG51D/G51D cortex were significant due to down-regulation of proteins involved in oxidative phosphorylation (NDUFAB1, COX5A, NDUFB8), and in the case of PD dopamine transport (SLC18A2)." (PMID 40574971, 2025).
acute myocardial infarction (4 papers, 2020 to 2025). Necrosis of the myocardium, as a result of interruption of the blood supply to the area. "The downregulation of COX5A expression increases the apoptosis rate at the onset of myocardial infarction." (PMID 37007963, 2023). "COX5A reduction has also been demonstrated close correlation with acute myocardial infarction and diabetes." (PMID 32349668, 2020). "Further, they identified two microRNAs that acted to inhibit Cox5a after a heart attack." (PMID 34518647, 2021).
cardiomyopathy (3 papers, 2021 to 2023). A disease of the heart muscle or myocardium proper. "We investigate the roles of COX5A in DOX-induced cardiomyopathy and explore the underlying mechanisms." (PMID 37373547, 2023). "The cardioprotective roles of COX5A were further explored in this study in DOX-induced cardiomyopathy." (PMID 37373547, 2023). "Our present findings provide the evidence that COX5A protected against DOX-induced cardiomyopathy via PI3K/Akt signaling." (PMID 37373547, 2023). "Thus, we identified that PI3K/Akt signaling was responsible for the COX5A-mediated protective role in DOX-induced cardiomyopathy." (PMID 37373547, 2023). "Therefore, we concluded that upregulation of COX5A attenuated DOX-induced cardiomyopathy in mice." (PMID 37373547, 2023). "Thus, we identified COX5A as a potential therapeutic target for DOX-induced cardiomyopathy." (PMID 37373547, 2023). "To explore the function of COX5A in DOX-induced cardiomyopathy, we specifically overexpressed COX5A in myocardium via a tail vein injection of recombinant adeno-associated virus serum type 9 carrying COX5A (AAV9-COX5A) and negative control (AAV9-NC) before DOX treatment." (PMID 37373547, 2023).
sleep disorder (3 papers, 2022 to 2025). A change from the patient's baseline sleeping pattern, in the hours slept and/or an alteration/dysfunction in the stages of sleep. "ATP5B, COX5A, GAPDH NDUFV2, SOD1, UQCRC1, and UQCRC2 have been reported as sleep deprivation and sleep disorder-related genes, and these studies have contributed to the development of candidate biomarkers for the diagnosis and treatment of plateau-induced sleep disorders." (PMID 36860517, 2023).
breast carcinoma (2 papers, 2021). "Another study showed that the expression of COX5a is upregulated in breast cancer tissues compared with healthy tissues." (PMID 34685389, 2021). "High expression of both COX5A and AURKA significantly predicts poor relapse free survival (RFS) in breast cancer patients (HR = 2.400, log-rank p < 0.001)." (PMID 34593753, 2021).
diabetes (2 papers, 2020 to 2023). "Polymorphisms of genes involved in diabetes pathogenesis, including IL8RA, TXN, NR3C2, COX5A, and GCLC, significantly modulated the association between urinary As levels and the odds of diabetes in a general Spanish population." (PMID 37624175, 2023).
gastric cancer (2 papers, 2016 to 2025). A primary or metastatic malignant neoplasm involving the stomach. "Association between COX5A expression and clinicopathological characteristics in gastric cancer patients (n = 95)." (PMID 41184196, 2025). "To investigate the role of COX5A in oxidative phosphorylation and ATP synthesis in gastric cancer cells, we first downregulated COX5A expression in IM95 and SNU‐601GC cells, which exhibit high levels of COX5A expression, using shRNA." (PMID 41184196, 2025). "To validate the clinical relevance of COX5A, we analysed a cohort of 95 gastric cancer patients from our institution." (PMID 41184196, 2025). "In this study, quantitative real‐time PCR (qRT‐PCR) was used to measure COX5A mRNA expression in tumour and adjacent normal tissues from 95 gastric cancer (GC) patients." (PMID 41184196, 2025). "Analysis of public genomic data from the TCGA stomach adenocarcinoma dataset revealed a distinct pattern of COX5A expression during gastric cancer progression." (PMID 41184196, 2025). "Multivariate Cox regression analysis (adjusted for age, stage, and grade) identified COX5A as an independent prognostic factor for overall survival in gastric cancer (HR = 1.52, p < 0.01)." (PMID 41184196, 2025). "COX5A was found to be down-regulated in other cancers such as nasopharyngeal and gastric carcinomas." (PMID 27566066, 2016). "To elucidate the role of COX5A in the proliferation, migration, and invasion of gastric cancer (GC) cells, we employed shRNA to silence COX5A expression in IM95 and SNU‐601 GC cell lines, both of which exhibit high endogenous COX5A levels." (PMID 41184196, 2025). "However, despite the inhibition of PI3K/AKT signalling by Ly294002, ATP synthesis remained unaffected, further supporting the hypothesis that COX5A promotes ATP synthesis via a PI3K/AKT‐dependent mechanism to drive gastric cancer progression." (PMID 41184196, 2025). "Our study establishes COX5A as a dual‐functional regulator of gastric cancer (GC) progression, serving as a critical nexus between mitochondrial bioenergetics and oncogenic signalling pathways." (PMID 41184196, 2025). "Our findings indicate that COX5A activates the PI3K/AKT signalling pathway, which subsequently promotes proliferation, migration, and invasion in gastric cancer (GC) cells." (PMID 41184196, 2025).
Insulin resistance (2 papers, 2014 to 2023). Increased resistance towards insulin, that is, diminished effectiveness of insulin in reducing blood glucose levels. "We conducted a genome-wide promoter analysis of DNA methylation in skeletal muscle of HFD rats and demonstrated that hypermethylation of the Cox5a promoter was associated with concomitant mitochondrial dysfunction in skeletal muscle of HFD-induced insulin resistant rats." (PMID 25436770, 2014). "COX5A (cytochrome C oxidase subunit 5A) is the top oxidative marker related to mitochondrial function, which induces an imbalance in energy metabolism and insulin resistance." (PMID 37293508, 2023). "COX5A is related to mitochondrial dysfunction in insulin resistance." (PMID 37293508, 2023). "Correspondingly, our data demonstrate that FFA acutely induced the methylation of Cox5a promoter, indicating that this might be an early event in the pathogenesis of insulin resistance." (PMID 25436770, 2014). "Furthermore, downregulation of Cox5a resulted in decreased complex IV activity and cellular ATP content, which are plausibly related to the pathogenesis of subsequent insulin resistance." (PMID 25436770, 2014). "However, the main objective of our study is to investigate whether hypermethylation of Cox5a is associated with mitochondrial dysfunction in skeletal muscle of high-fat fed rats, which might be a potential mechanism for HFD-induced insulin resistance." (PMID 25436770, 2014).
lung carcinoma (2 papers, 2024). "Among them, a number of proteins related to mitochondrial biogenesis were upregulated in BrM lesions as compared to paired primary lung cancers, including NDUFAF2, SDHB, COX5A, and ATP5PO." (PMID 39593114, 2024).
lymph node metastasis (2 papers, 2012 to 2025). "Our analysis demonstrated that high COX5A expression was significantly linked to larger tumour size (p < 0.05), deeper invasion depth (p < 0.01), presence of lymph node metastasis (p < 0.01), and advanced TNM stage (p < 0.01)." (PMID 41184196, 2025).
memory impairment (2 papers, 2020 to 2022). "COX5A plays a vital role in aging-related memory impairment." (PMID 35990086, 2022). "Taken together, the decrease of COX5A in aged SAMP8 mice suggested that COX5A might contribute to age-related memory impairment." (PMID 32754029, 2020).
pulmonary arterial hypertension (2 papers, 2020 to 2022). Pulmonary arterial hypertension (PAH) is a group of diseases characterized by mean pulmonary artery pressure >20 mmHg and elevated pulmonary arterial resistance leading to right heart failure. "Previous research indicated that the dysregulation of COX5A significantly affects COX function, thereby causing mitochondrial dysfunction in skeletal muscle, pulmonary arterial hypertension, lactic academia, and central nervous system diseases." (PMID 33490242, 2020).
renal cell carcinoma (2 papers, 2021 to 2024). "However, gel-based proteomics showed that upregulation of COX5a occurs in renal cell carcinomas." (PMID 34685389, 2021).
brain infarction (1 paper, 2020). Tissue necrosis in any area of the brain, including the cerebral hemispheres, the cerebellum, and the brain stem. "HI induced a severe neurological dysfunction, brain infarction, and cell apoptosis as well as obvious neuron loss in neonatal rats, in corresponding to the decrease on the expression of COX5A in both sides of the brain." (PMID 32349668, 2020).
Cachexia (1 paper, 2021). Severe weight loss, wasting of muscle, loss of appetite, and general debility related to a chronic disease. "To investigate this point, we verified the mitochondrial function-associated gene expression of Cox5a, and citrate synthase, directly related to oxidative metabolism in the muscle of cancer cachexia groups." (PMID 34943780, 2021).
cognitive decline (1 paper, 2022). "Further, cytochrome c oxidase subunit Va (COX5A) in the hippocampus plays a critical role in age-related cognitive decline through the regulation of BDNF/ERK1/2 signaling pathway." (PMID 36406589, 2022).
Cognitive impairment (1 paper, 2020). Abnormal cognition is characterized by deficits in thinking, reasoning, or remembering. "Our study first supplies supporting evidence that COX5A is a significant and treatable component of cognitive impairment induced by brain senescence-associated diseases." (PMID 32754029, 2020). "COX5A overexpression rescued the repression of the BDNF/ERK1/2 pathway, which is in line with the results presented in previous studies, thereby indicating that the BDNF/ERK1/2 pathway is a molecular therapeutic pathway in the treatment of cognitive impairment in Tg AD mice." (PMID 32754029, 2020).
COVID-19 (1 paper, 2024). A disease caused by infection with severe acute respiratory syndrome coronavirus 2. "This study identified 30 nodes associated with cytokine storm, ARDS, and inflammatory process of COVID-19, namely, IL-6, IL-6R, NF-κB, IL-2, IL-2RA, IFNA2, IFNAR1, COX5A, and COX411." (PMID 39640429, 2024).
dilated cardiomyopathy (1 paper, 2023). Cardiomyopathy which is characterized by dilation and contractile dysfunction of the left and right ventricles. "We quantified COX5A, COX5B, and SOD2 protein levels in heart samples from patients with end-stage dilated cardiomyopathy (DCM) or subjects without obvious cardiovascular diseases, and observed that COX5A and SOD2 were clearly down-regulated in heart tissues with DCM." (PMID 37373547, 2023).
emphysema (1 paper, 2022). "Our results show a significant decrease in COX5A mRNA expression in emphysema compared to nonsmokers." (PMID 35884802, 2022).
Failure to thrive (1 paper, 2023). Failure to thrive (FTT) refers to a child whose physical growth is substantially below the norm. "Previous reports showed that down-regulation of COX5A significantly decreases COX activity, leading to mitochondrial dysfunction, pulmonary arterial hypertension, lactic academia, hypoglycemia, growth delay, and failure to thrive." (PMID 37373547, 2023).
glioblastoma (1 paper, 2022). The most malignant astrocytic tumor (WHO grade IV). "Both COX5A and the gene encoding another subunit of complex III, UQCRB, are downregulated in glioblastoma patients compared to healthy individuals." (PMID 36142793, 2022).
glioma (1 paper, 2022). A benign or malignant brain and spinal cord tumor that arises from glial cells (astrocytes, oligodendrocytes, ependymal cells). "In contrast, when compared to expression in gliomas of lower grade malignancy, COX5A expression is significantly increased in GBM, and UQCRB expression is at approximately the same level." (PMID 36142793, 2022). "Most cellular metabolism genes investigated in glioma cell lines (ATP5A1, COX5A, CPT2, PFKL, and UQCRFS1) were found to be statistically downregulated." (PMID 36142793, 2022).
HCMV infection (1 paper, 2022). "In addition, the genes relate to mitochondrial biogenesis (PGC-1α, TFAM, and NRF1) and oxidative phosphorylation (ATP5G1 and Cox5a) were also decreased after HCMV infection." (PMID 35359726, 2022).
ischemic heart disease (1 paper, 2021). "In summary, we found significantly decreased Cox5a expression in the hearts of MI rats, suggesting that Cox5a may contribute to the pathophysiology of ischemic heart disease." (PMID 34518647, 2021).
leukemia (1 paper, 2025). A malignant (clonal) hematologic disorder, involving hematopoietic stem cells and characterized by the presence of primitive or atypical myeloid or lymphoid cells in the bone marrow and the blood. "Further, CRISPR targeting of these COX4I1‐regulated Complex IV members (such as COX5A, COX6B1, etc.)also exhibits a selective impact on blood cancer cells, emphasizing a unique addiction of leukemia cells to the intact functional Complex IV." (PMID 39716856, 2025).
prion disease (1 paper, 2025). A transmissible disease that is caused by a protein that is able to induce abnormal folding of normal cellular proteins, leading to characteristic spongiform brain changes, which are associated with neuronal loss without an inflammatory response. "We compare down/up-regulated proteins from C− versus 5RINM with altered proteins related to chemical carcinogenesis, reactive oxygen species (e.g., down-regulated P48962/Slc25a4, P51881/Slc25a5, Q9CQQ7/Atp5f1, or P12787/Cox5a), and prion disease (e.g., down-regulated Q05144/Rac2)." (PMID 40006055, 2025).
Tinnitus (1 paper, 2024). Tinnitus is an auditory perception that can be described as the experience of sound, in the ear or in the head, in the absence of external acoustic stimulation. "Specifically, we found that the expression level of Cox5a increased ≈22 folds in the ACC of tinnitus mice compared with healthy controls." (PMID 38009798, 2024).
Ureteral obstruction (1 paper, 2021). Obstruction of the flow of urine through the ureter. "In neonatal rat kidney, COX5a is upregulated after partial unilateral ureteral obstruction." (PMID 34685389, 2021).